EGFR (epidermal growth factor receptor)
Diseases named in the same sentence as EGFR in open-access papers (continued):
Sharing a sentence is not in itself a finding about the gene and the disease.
non-small cell lung carcinoma (continued). "In non-small cell lung cancer (NSCLC), secretion of oncostatin-M (OSM), a member of the IL-6 cytokine family, by cancer-associated fibroblasts increases STAT3 activity through activation of JAK1 and is a possible mechanism of resistance to targeted therapy such as EGFR and MEK inhibitors." (PMID 33521321, 2020). "However, mutant EGFR is oncogenic in non-small cell lung cancer." (PMID 30845713, 2019). "Non-small cell lung cancer (NSCLC) with activating mutations in the epidermal growth factor receptor (EGFR) such as an exon 19 deletion and L858R mutation responds to first- and second-generation EGFR-tyrosine kinase inhibitors (EGFR-TKIs), including gefitinib, erlotinib, and afatinib." (PMID 30651547, 2019). "For example, the epidermal growth factor receptor (EGFR) T790M mutation impairs the interaction of inhibitory chemicals with the ATP-binding pockets of protein kinases, leading to acquired resistance to first- and second-generation EGFR-TKIs in non-small-cell lung cancer." (PMID 31422383, 2019). "Here we showcase the capability of this fully integrated platform to detect and quantify non-small cell lung carcinoma (NSCLC) rare genetic mutants (EGFR T790M) with precision cell-free DNA (cfDNA) standards." (PMID 31862911, 2019). "Clonogenic assays of EGFR mutant (n = 6) and wild-type (n = 9) non-small cell lung carcinoma (NSCLC) cell lines were performed independently by two oncologists." (PMID 31349558, 2019). "In addition, detection of EGFR and E-cadherin expression in multiple epithelial cancers reveals a significant correlation for the following types of cancers (head and neck, colorectal cancer, and non-small-cell lung carcinoma (NSCLC)) out of seven tested." (PMID 31015417, 2019). "In the majority of cases, ADSC in small biopsy specimens is misdiagnosed as SqCC or poorly differentiated SqCC referring to non-small cell carcinoma (NSCC) favor SqCC due to biased sampling of the lesion, which may cause the neglect of EGFR mutation testing in these cases." (PMID 31221183, 2019). "Aberrant activation of EGFR represents a common event in non-small cell lung carcinoma (NSCLC) and activates various downstream signaling pathways." (PMID 30177836, 2019). "Further investigation of resistance formation to EGFR tyrosine kinase inhibitors using drug-adapted non-small cell lung cancer cell lines revealed that the origin of the resistance-mediating T790M EGFR mutation may differ in different cell line systems and patients." (PMID 35582596, 2019). "Although the mechanisms underlying this phenomenon remains to be fully clarified, SCLC cells might arise from a minority of preexistent cells which were exposed to EGFR-TKIs and either derived from the multipotent stem cells, or from non-small cell lung cancer cells by transdifferentiating." (PMID 30404198, 2018). "Notably, RN765C is very potent towards the non-small cell lung cancer PDX LG1049 which carries the EGFR exon 19 deletion and T790M mutation, the latter is known to drive resistance to first generation TKIs (e.g. erlotinib and gefitinib) of EGFR." (PMID 30323890, 2018). "First-generation EGFR tyrosine kinase inhibitors, including gefitinib and erlotinib, are the first-line treatment against advanced non-small cell lung cancers with EGFR activating mutations, especially in Asians, females, never smokers, and/or patients with adenocarcinoma." (PMID 29784046, 2018). "Anti-EGFR therapies, including tyrosine kinase inhibitors (TKIs) and monoclonal antibodies, have been developed and are already available for treatment of different cancers such as non-small cell lung cancer (NSCLC) and colorectal cancer, making EGFR inhibitors an attractive option for TNBC therapy." (PMID 29795369, 2018). "EGFR activation by oncogenic mutations induces phosphorylation of BECN1 at Y229, Y233, and Y352, which suppress autophagy and enhance tumorigenesis in a NSCLC (non-small cell lung carcinoma) xenograft model." (PMID 30370269, 2018).
non-small cell lung carcinoma (continued). "Thus, EGFR is a good candidate for developing non-small cell lung cancer vaccines." (PMID 30400835, 2018). "It was followed by a rapid decrease, and this is most likely associated with response to treatment, as recently demonstrated for non-small cell lung carcinoma (NSCLC) treated with EGFR tyrosine kinase inhibitors." (PMID 28743309, 2017). "For example, an anti-EGFR x anti-cMet BsAb is able to simultaneously bind both antigens which are highly expressed on non-small cell lung carcinoma (NSCLC) cells." (PMID 29138497, 2017). "The identification of ALK rearrangements, found in approximately 5% of non-small-cell lung cancers (NSCLCs), and the success of tyrosine-kinase inhibitors (TKI) (crizotinib, ceritinib, alectinib and brigatinib), have provided a breakthrough similar to the discovery of EGFR mutations and treatment." (PMID 28938646, 2017). "ALK and EGFR tyrosine-kinase inhibitors showed better activity and efficacy than standard chemotherapy in the first and second line treatment settings, leading to a clear advantage in overall survival of advanced non-small cell lung cancer patients harboring these genetic alterations." (PMID 28938691, 2017). "Therefore, we focused on most non-small cell lung cancers including also squamous cell carcinoma, which are unlikely to be EGFR mutated." (PMID 28139704, 2017). "A recent study revealed that Beclin-1-mediated autophagy enhances the effectiveness of EGFR tyrosine kinase inhibitor (TKI) therapy in non-small cell lung carcinoma (NSCLC) cells." (PMID 29113343, 2017). "Shp2 is also required for proliferation in EGFR-inhibitor resistant non-small cell lung carcinoma (NSCLC) cells." (PMID 28085101, 2017). "The epidermal growth factor receptor (EGFR) is the major driver of non-small cell lung carcinoma (NSCLC)." (PMID 28714950, 2017). "In addition, oncogenic somatic mutations in specific sites of the EGFR gene, such as EGFR variant III (EGFRvIII) in glioblastoma multiforme (GBM) and activating EGFR mutations in non-small cell lung cancer (NSCLC), have been reported to be closely associated with tumorigenesis." (PMID 27833557, 2016). "The identification of mutations within the epidermal growth factor receptor (EGFR), and the finding that these mutations make tumors exquisitely sensitive to EGFR tyrosine kinase inhibitors (TKIs), has revolutionized treatment of non-small-cell lung cancer (NSCLC)." (PMID 26366316, 2015). "Epidermal growth factor receptor (EGFR) mutations, v‐Ki‐ras2 Kirsten rat sarcoma (KRAS) mutations and anaplastic lymphoma kinase (ALK) gene rearrangements represent driver mutations that are frequently assessed on initial evaluation of non-small-cell lung cancer (NSCLC)." (PMID 26555338, 2015). "Somatic mutations in the epidermal growth factor receptor (EGFR) gene have been identified as a major determinant of the clinical efficacy of treatment with EGFR tyrosine kinase inhibitors (TKIs) such as gefitinib and erlotinib in patients with non-small cell lung cancer (NSCLC)." (PMID 25115383, 2014). "For example, treatment with the monoclonal anti-EGFR antibody cetuximab and the EGFR tyrosine kinase inhibitor erlotinib (in monotherapy or in combination with cytotoxic drugs) has resulted in improved survival in patients with colorectal cancer and non-small-cell lung cancer." (PMID 24457059, 2014). "This case is interesting for the choice of second-line treatment in non-small-cell lung cancer and, moreover, for the possibility of a complete and prolonged response to erlotinib even in patients without the activating mutation of epidermal growth factor receptor." (PMID 24661457, 2014). "The aim of this study was to determine the frequency of EGFR, KRAS, BRAF, and HER-2 mutations in brain metastases from non-small cell lung carcinomas (BM-NSCLC)." (PMID 23930206, 2013).
non-small cell lung carcinoma (continued). "In the search for the molecular basis of drug resistance in patients with non-small-cell lung cancers (NSCLCs), Y845 and some other phosphorylation sites such as Y1045 and Y1068 have been identified as prominently phosphorylated sites in many gefitinib-resistant EGFR mutants." (PMID 23702846, 2013). "Although monotherapy of anti-EGFR mAbs exhibits a limited efficacy in clinical trials, their combination with radiotherapy and/or chemotherapy has shown promising outcomes in treating advanced squamous cell cancer of head and neck, non small cell lung cancer and colorectal cancers." (PMID 23976954, 2013). "Moreover, a recent study demonstrated that EGFR tyrosine kinase inhibitors such as gefitinib and erlotinib, already used clinically as chemotherapy for non-small cell lung cancer, inhibited RIP2 tyrosine phosphorylation and MDP-induced cytokine release, but not in an EGFR-dependent manner." (PMID 23675299, 2013). "Epidermal growth factor receptor (EGFR) mutations, such as deletions in exon 19 and point mutations in exon 21, are considered the most reliable predictive factors of outcome after treatment of non-small cell lung cancer (NSCLC) with EGFR tyrosine kinase inhibitors (EGFR-TKIs)." (PMID 23927790, 2013). "Thus, we report on an anaplastic lymphoma kinase-positive non-small cell lung carcinoma patient with concomitant occurrence of epidermal growth factor receptor and V-Ki-ras2 Kirsten rat sarcoma viral oncogene homolog mutations upon development of crizotinib-resistance." (PMID 24279718, 2013). "A recent example of this is a test for epidermal growth factor receptor (EGFR) mutation in patients with advanced non-small-cell lung cancer, which determines whether or not the first-line EGR tyrosine kinase inhibitor therapy is indicated." (PMID 22752797, 2012). "Since not only activating mutations of the EGFR gene exist, but secondary resistance to TKI-therapy can be a result of additional mutations thorough analysis and exact characterization of EGFR mutations by sequence analysis in non-small cell lung cancer should be performed." (PMID 23088930, 2012). "Overexpression of the epidermal growth factor receptor type 1 (EGFR, HER1) has been shown to play a major role in the pathogenesis of a number of malignancies including non-small cell lung carcinoma (NSCLC)." (PMID 22710607, 2012). "A good example is the inherent resistance of tumours to anti-EGFR antibody and small molecule therapies resulting from the presence of a KRAS mutation and the sensitivity of patients to the gefitinib and erlotinib EGFR inhibitors in non-small cell lung cancer patients with activating EGFR mutations." (PMID 21649578, 2011). "Recent studies have shown that KRAS mutations are negative predictors of benefit from both adjuvant chemotherapy and anti-EGFR directed therapies for non-small cell lung carcinoma (NSCLC)." (PMID 29147262, 2011). "Gefitinib is a tyrosine kinase inhibitor (TKI) of the epidermal growth factor receptor (EGFR) especially effective in tumors with activating EGFR gene mutations while EGFR wild-type non small cell lung cancer (NSCLC) patients at present do not benefit from this treatment." (PMID 22111840, 2011). "In particular, they have been used to treat non-small cell lung carcinomas (NSCLC) where EGFR is frequently overexpressed or activated due to point mutations." (PMID 20385023, 2010). "The EGFR gene is rarely amplified in human cancers, but the increased EGFR gene copy number with balanced chromosome 7 polysomy in cancer cells is relatively frequent, in ∼24–40% of patients with non-small cell lung cancer, squamous-cell carcinoma of the head and neck or colorectal cancer." (PMID 20664595, 2010).
non-small cell lung carcinoma (continued). "In an illustrative application, we tested as a hypothesis of interest that the EGFR 15/18 bp deletions found in 5–20% of non-small cell lung cancers might have arisen during the development of normal lung tissue and been enriched due to a selective replication advantage." (PMID 19789704, 2009). "Finally, in vivo efficacy of A-928605 was assessed in the oncogene-addicted cell line and in a neuroblastoma model as a single agent as well as in combination with clinically approved therapeutics targeting EGFR in models of pancreatic and non-small cell lung cancers." (PMID 19732452, 2009). "For example, EGFR and KRAS mutations are reported to be mutually exclusive in non-small cell lung carcinoma, which means that genes selected by their correlation with EGFR mutation status may be not regulated by EGFR, but instead regulated by KRAS." (PMID 19517027, 2008). "Epidermal growth factor receptor (EGFR) overexpression is observed in significant proportions of non-small cell lung carcinomas (NSCLC)." (PMID 19455247, 2007). "For example, in colorectal cancer and non-small cell lung cancer, HDVC combined with epidermal growth factor receptor (EGFR) and PARP inhibitors demonstrated superior therapeutic outcomes." (PMID 41403402, 2026). "In EGFR mutant non-small-cell lung cancer, the CDK4/6 inhibitor Palbociclib can reverse the resistance to the EGFR inhibitor Osimertinib." (PMID 40563591, 2025). "Integrating antibodies against EpCAM, HER2, and EGFR in CTC isolation platforms improved capture rates and provided a more comprehensive profile of CTC populations in breast and non-small cell lung cancer patients." (PMID 40076201, 2025). "Non-small cell lung cancer (NSCLC) is a challenging disease, with the epidermal growth factor receptor (EGFR) being a key target for new, effective treatments crucial for the signaling pathways regulating cancer cell survival." (PMID 40076971, 2025). "Previous studies have indicated that the concomitant use of EGFR inhibitors and KRAS inhibitors can yield clinical benefits in the treatment of non-small cell lung cancer (NSCLC) and colorectal cancer." (PMID 40689200, 2025). "While ICI have revolutionized the treatment of non-small cell lung cancer (NSCLC), prior studies indicate limited benefit in patients with EGFR-mutant lung adenocarcinoma." (PMID 41162774, 2025). "Alterations in exons 19 and 21 are most common in non-small cell lung cancer (NSCLC), explaining why this type of cancer is sensitive to EGFR-TKIs." (PMID 38888847, 2025). "Gefitinib (GEF), a first-generation epidermal growth factor receptor (EGFR) tyrosine kinase inhibitor (TKI), has become a widely used small-molecule targeted drug in the treatment of non-small cell lung cancer (NSCLC)." (PMID 40932871, 2025). "Gefitinib, one of the first-generation epidermal growth factor receptor (EGFR)-tyrosine kinase inhibitors, was approved by the US Food and Drug Administration (FDA) to treat metastatic non-small cell lung cancer in 2015." (PMID 39926646, 2025). "In non-small cell lung cancer (NSCLC), EGFR alterations act as oncogenic drivers, revolutionizing patient outcomes with the use of tyrosine kinase inhibitors (TKIs) targeting EGFR." (PMID 40364160, 2025). "In non-small cell lung cancer (NSCLC), PTP activity mediates resistance to EGFR inhibitors, such as osimertinib, by modulating the PI3K/AKT signaling pathway." (PMID 40001520, 2025). "In non-small cell lung cancer (NSCLC), JMJD8 enhances the proliferation and invasion of cancer cells by stabilizing the epidermal growth factor receptor (EGFR), thereby inhibiting the degradation of the overexpressed EGFR." (PMID 40761260, 2025). "In non-small cell lung cancer (NSCLC), cells treated with the epidermal growth factor receptor (EGFR) inhibitor gefitinib exhibited reduced E-cadherin levels and increased vimentin expression in resistant cells." (PMID 40738896, 2025).
non-small cell lung carcinoma (continued). "In non-small cell lung cancer (NSCLC), the long-term use of EGFR-TKIs leads to drug resistance, characterized by cholesterol accumulation in lipid rafts." (PMID 40722703, 2025). "Epidermal growth factor receptor (EGFR) and its downstream signaling pathway are common oncogenic pathways in human non-small cell lung cancer (NSCLC)." (PMID 39317868, 2025). "In non-small-cell lung cancer (NSCLC), for example, EGFR-TKIs have been shown to downregulate PD-L1 expression, potentially sensitizing tumors to PD-1/PD-L1 blockade." (PMID 41013723, 2025). "For instance, the E3 ubiquitin ligase FBXL2, a member of the conserved F-box protein family, targets both EGFR and tyrosine kinase inhibitor (TKI)-resistant EGFR mutants for proteasome-mediated degradation in EGFR-driven non-small cell lung cancer (NSCLC)." (PMID 41226319, 2025). "In non-small cell lung cancer (NSCLC), EGFR palmitoylation regulates the interaction between PI3K regulatory subunit PIK3R1 (p85) and EGFR, enhancing recruitment of PI3K heterodimers to the plasma membrane and amplifying downstream AKT activation." (PMID 40977744, 2025). "In non-small cell lung cancer, Kremen2 drives tumor progression by preventing SOCS3-mediated ubiquitination of EGFR." (PMID 40170095, 2025). "Currently precise target treatment based on gene status significantly improved the outcome for patients with non-small cell lung cancer (NSCLC) and epidermal growth factor receptor (EGFR) was the most important gene." (PMID 41573643, 2025). "ScFv-based, EGFR-targeted CAR-T cells have shown some efficacy in various types of solid tumors, including triple-negative breast cancer (TNBC), non-small cell lung cancer (NSCLC), multiple glioblastoma (GBM), and ESCC." (PMID 40722671, 2025). "Oncoproteins, including EGFR, GRB2, and SRC, have been reported to be enriched in the non-small cell lung cancer (NSCLC) exosomes, which promote the cancer’s development." (PMID 40006514, 2025). "Using the SWISS-MODEL server, we generated accurate 3D models for EGFR, ALK, KRAS, and PD-1, which represent key oncogenic and immunomodulatory targets in non-small cell lung cancer (NSCLC)." (PMID 40927719, 2025). "In the eleven included studies, non-small cell lung cancer (NSCLC) and breast cancer were mainly focused on, with AI models developed that predict biomarkers such as EGFR, HER-2, Ki-67, and T790M." (PMID 40868304, 2025). "To investigate the increasing role of ginsenoside Rg3 on the efficacy of EGFR-TKI in non-small cell lung cancer, we systematically evaluated the effect of ginsenoside Rg3 in combination with EGFR-TKI in non-small cell lung cancer treatment." (PMID 40732366, 2025). "A notable example of how VUS can affect clinical practice is underscored by the epithelial growth factor receptor gene (EGFR), a member of the receptor tyrosine kinase (RTK) family and known oncogene, common in non-small cell lung cancers (NSCLC) among others." (PMID 39533106, 2025). "Mechanistic studies have shown that IPTF effectively represses the malignant proliferation phenotype of non-small cell lung cancer A549 cells by synergistically inhibiting two key signaling pathways: PI3K/AKT and EGFR-MAPK." (PMID 41008250, 2025). "Osimertinib, the first approved third-generation epidermal growth factor receptor (EGFR)-tyrosine kinase inhibitor (TKI), exhibits notable efficacy in EGFR-mutant non-small cell lung cancer (NSCLC)." (PMID 41326340, 2025). "Combinatorial therapies are essential for treating advanced non-small cell lung cancer (NSCLC), particularly overcoming resistance to third-generation epidermal growth factor receptor (EGFR) like osimertinib (OSI)." (PMID 40922739, 2025). "The abnormal expression and overactivation of the epidermal growth factor receptor (EGFR), a typical cancer marker for non-small cell lung cancer (NSCLC), are closely related to the tumorigenesis and progression of NSCLC." (PMID 39910656, 2025).